HNF1A (HNF1 homeobox A)
Diseases named in the same sentence as HNF1A in open-access papers (continued):
Sharing a sentence is not in itself a finding about the gene and the disease.
type 2 diabetes (continued). "The assay has been optimized and its performance validated on 1000 clinical blood plasma samples from individuals with young-adult onset diabetes, including groups of individuals with different variants in the HNF1A gene." (PMID 34939081, 2022). "SGLT‐2 inhibitors have also been shown to reduce blood glucose in HNF1A MODY but cause higher glycosuria compared to patients with type 2 diabetes." (PMID 35445424, 2022). "Antennary fucosylation alterations in plasma glycoproteins have been previously proposed and tested as a biomarker for differentiation of maturity onset diabetes of the young (MODY) patients carrying a functional mutation in the HNF1A gene." (PMID 33765222, 2021). "To resolve HNF1A genotype-phenotype complexity, we sought to evaluate the function of 73 HNF1A missense alleles which were observed almost 26K times in the exomes of ∼13K multi-ethnic type 2 diabetes case subjects and control subjects." (PMID 32910913, 2020). "We were able to mitigate error associated with handling data from two centers with methodological differences by benchmarking several HNF-1A variants (benign, type 2 diabetes risk, and MODY) in both laboratories." (PMID 32910913, 2020). "In this study, we investigated the functional impact of 73 missense variants in HNF1A, detected by exome sequencing of a multi-ethnic type 2 diabetes case-control cohort from four different mechanistic angles." (PMID 32910913, 2020). "As a result, the algorithm correctly identified 92/99 (92.9%) of patients with type 1 diabetes, 78/92 (84.8%) patients with type 2 diabetes, 50/77 (64.9%) HNF1A MODY patients, and 46/88 (52.3%) of GCK mutation carriers." (PMID 30778899, 2019). "Genome-wide association analysis (GWAS) results revealed a correlation between the HNF1α mutations and the potential risk of developing type 2 diabetes." (PMID 31223625, 2019). "Double knockdown of the HNF1α gene in mice causes multiple symptoms such as hepatomegaly, phenylketonuria, Fanconi syndrome, and noninsulin-dependent diabetes mellitus." (PMID 31223625, 2019). "HNF-1α-deficient mice and patients suffering from maturity-onset type 3 diabetes develop type 2 diabetes and renal Fanconi syndrome characterized by increases in urinary glucose levels." (PMID 29717156, 2018). "miR-122, the expression of which is regulated by several transcription factors, such as HNF1A, was recently reported to be associated with type 2 diabetes (T2DM) and hepatocellular carcinoma." (PMID 30155490, 2018). "Consistent with an important role in hepatic functions, HNF1A locus and genetic variations in HNF1A are associated with maturity-onset diabetes of the young (MODY3), type 2 diabetes, and coronary artery disease." (PMID 29066969, 2017). "Common variants in HNF1α are also associated with increased risk of developing type 2 diabetes (T2D)." (PMID 28493909, 2017). "This variant causes an amino acid change from glutamate to lysine in the HNF1A gene, one of the genes which when mutated causes maturity onset diabetes of the young (MODY)." (PMID 29376044, 2017). "Mutations in the HNF1A gene account for approximately 70% of cases of maturity onset diabetes of the young (MODY)." (PMID 27366637, 2016). "Both TCF7L2 variants (rs7903146 and rs12255372), HHEX rs1111875, and HNF1A rs7957197 were associated with increased risk of type 2 diabetes." (PMID 27551309, 2016). "We identified two sequence variations in the HNF-1α gene in siblings with divergent clinical manifestations of type 2 diabetes, metabolic syndrome and HNF1A-MODY mutations." (PMID 27142837, 2016). "For example, several GWAS loci for type 2 diabetes contain genes known to harbour causal coding variants for rare Mendelian syndromes related to type 2 diabetes (e.g. HNF1A, HNF1B, WFS1, PPARG, KCNJ11, HNF4A, GCK)." (PMID 26702037, 2015). "Whole-exome sequencing in a Latino population revealed a rare missense variant in HNF1A (c.1522G > A [p.E508K]) was associated with type 2 diabetes prevalence." (PMID 25774817, 2015).
type 2 diabetes (continued). "Germline heterozygous mutations of HNF1A have been found responsible for type 3 MODY (maturity-onset diabetes of the young)." (PMID 25793983, 2015). "Polymorphisms in the Hnf1a gene are associated with risk for Type 2 diabetes and coronary heart disease." (PMID 23463770, 2013). "The hepatocyte nuclear factor-1α (HNF1α), which haploinsufficiency causes the Maturity-onset diabetes of the young type 3 (MODY3), also appears to modulate SHP expression via the FXR pathway." (PMID 22577560, 2012). "Mutations in hepatocyte nuclear factor 1α (HNF-1α) is associated with maturity-onset diabetes of the young type 3." (PMID 22577560, 2012). "In humans, heterozygous germline mutations of the HNF1A gene, encoding HNF-1α, are the cause of maturity-onset diabetes of the young type 3 (MODY3)." (PMID 22672869, 2012). "The population-specific HNF1A G319S variant was associated with incident type 2 diabetes in Aboriginal Canadians." (PMID 21208426, 2011). "We have previously reported that a glycine to serine substitution at codon 319 (G319S) of the HNF1A gene in an Aboriginal population was significantly associated with increased type 2 diabetes prevalence in cross-sectional analysis." (PMID 21208426, 2011). "A population-specific G319S polymorphism in HNF1A was previously identified in Aboriginal Canadians who have a high prevalence of type 2 diabetes." (PMID 21208426, 2011). "In the first model adjusted for age and sex, the HNF1A G319S polymorphism was associated with increased risk for developing type 2 diabetes (odds ratio [OR] 3.24 [95% CI 1.90-5.53])." (PMID 21208426, 2011). "The presence of cigarette smoking appears to amplify the predisposition to the development of type 2 diabetes in carriers of HNF1A G319S." (PMID 21208426, 2011). "The HNF1A G319S carrier status was associated with incident type 2 diabetes (odds ratio [OR] 3.78 [95% CI 2.13-6.69]) after adjustment for age, sex, hypertension, triglyceride, HDL cholesterol, and waist circumference." (PMID 21208426, 2011). "In a recent report of large-scale association analysis, a type 2 diabetes susceptibility locus near HNF1A was identified in predominantly European descent populations." (PMID 21208426, 2011). "One region, upstream of the gene FAM78B, contains three binding sites for the transcription factor PPARG and two binding sites for HNF1A, both previously implicated in the pathology of type 2 diabetes." (PMID 22216000, 2011). "In a prospective cohort study from Scandinavian countries, a functional variant, HNF1A I27L, was associated with increased future risk for type 2 diabetes in Scandinavian countries (Hazard Ratio 1.2 [95% CI 1.1-1.3])." (PMID 21208426, 2011). "We found that the HNF1A G319S polymorphism was associated with increased risk of developing type 2 diabetes after adjustment for previously reported baseline clinical risk factors." (PMID 21208426, 2011). "Recently, a type 2 diabetes susceptibility locus near HNF1A was identified in large-scale association analysis of predominantly European descent populations." (PMID 21208426, 2011). "In an Aboriginal Canadian population, a private polymorphism, HNF1A G319S, was associated with increased prevalence of type 2 diabetes." (PMID 20716378, 2010). "HNF1A encodes the transcription factor hepatocyte nuclear factor 1 alpha and is the gene most commonly implicated in the pathogenesis of symptomatic Maturity-onset diabetes of the young (MODY)." (PMID 19672314, 2009). "Mutations in the HNF-1α gene cause Maturity-onset diabetes of the young (MODY)." (PMID 39228912, 2024). "We observed a significant association between HNF1A variants and type 2 diabetes in the population of European ancestry (OR 1.46 [95% CI 1.00, 2.13], p=0.049), but not in those of African ancestry (OR 1.10 [95% CI 0.77, 1.58], p=0.60) or Hispanic-Latino ancestry (OR 1.00 [95% CI 0.60, 1.64], p=1.0)." (PMID 36216889, 2023).
type 2 diabetes (continued). "Moreover, we demonstrate that overall polygenic susceptibility to type 2 diabetes affects the association between rare HNF1A variants in functional domains and type 2 diabetes risk in European-ancestry populations." (PMID 36216889, 2023). "Furthermore, a higher PRS exacerbated the effect of the functional HNF1A variants on type 2 diabetes in the European ancestry population (pinteraction=0.037)." (PMID 36216889, 2023). "Rare HNF1A variants that are predicted to impair protein function are associated with increased risk of type 2 diabetes in individuals of European ancestry (OR 1.46, p=0.049), particularly when the variants are located in the functional domains (OR 1.89, p=0.002)." (PMID 36216889, 2023). "We also tested whether the PRS affects the association between HNF1A variants and type 2 diabetes risk by including an interaction term." (PMID 36216889, 2023). "For example, rare variants in the hepatocyte nuclear factor 1 homeobox A gene (HNF1A), which encodes a transcription factor involved in pancreatic beta cell development and function, are responsible for 30–65% of all diagnoses of maturity-onset diabetes of the young." (PMID 36216889, 2023). "Whether the effect of these rare HNF1A variants on type 2 diabetes is exacerbated or attenuated by an individual’s overall genetic susceptibility to type 2 diabetes, as shown for other conditions, has so far not been reported." (PMID 36216889, 2023). "Furthermore, HNF1A (rs1169288) variant is associated with an increased risk of type 2 diabetes and dysglycemic status in normal-weight Japanese individuals." (PMID 35873425, 2022). "The genes regulated by hepatic nuclear factors, Hnf1A (n = 112 target molecules in the dataset) and Hnf4A (n = 527) TRs, whose mutations are known to cause maturity-onset diabetes of the young (MODY) and insulin-independent diabetes mellitus, were predicted to be inhibited by CUR." (PMID 35017319, 2022). "Defects in HNF1A gene are known to cause maturity onset diabetes of the young type 3 (MIM#600496)." (PMID 35109885, 2022). "Similarly, in our studies using hiPSCs isogenic lines generated through the introduction of mutation in hepatocyte nuclear factor 1A (HNF1A), we aimed to model the endothelial state of patients with maturity onset diabetes of the young (HNF1A-MODY)." (PMID 33260307, 2020). "The majority of HNF1A variants were identified in both type 2 diabetes case subjects and control subjects, and for the few observed exclusively in type 2 diabetes case subjects, they were identified with a frequency of either one or two case subjects per variant." (PMID 32910913, 2020). "Moreover, heterozygous mutations in some of these genes, PDX1 and HNF1α, are also responsible for different monogenic forms of maturity onset diabetes of the young (MODY 4 and MODY 5)." (PMID 33101198, 2020). "HNF1A gene mutations are frequently associated with type 2 diabetes." (PMID 28116330, 2017). "Therefore one family member had classical type 2 diabetes including metabolic syndrome aggravated by a genetic predisposition in the form of HNF1A-MODY." (PMID 27142837, 2016). "In this respect, a better comprehension of the gene networks that interact with HNF1A/MODY3 could be extremely useful in dissecting the molecular aspects underlying the variability of insulin secretion defects in type 2 diabetes." (PMID 27667715, 2016). "Our results show that mutations in HNF4A and HNF1A genes might account for this early-onset inherited type 2 diabetes." (PMID 26981542, 2016). "Mutations or common variants of HNF1A gene have also been associated with risk of type II diabetes." (PMID 25793983, 2015). "In humans, Hnf1a mutations are the most common cause of maturity-onset diabetes of the young." (PMID 23463770, 2013). "We aimed to investigate the association of the HNF1A G319S polymorphism with incident type 2 diabetes and to assess whether clinical risk variables for type 2 diabetes influence the association in an Aboriginal population." (PMID 21208426, 2011).
type 2 diabetes (continued). "We aimed to determine the association of the HNF1A G319S variant with the incidence of type 2 diabetes and to assess whether clinical risk variables for type 2 diabetes influence this association." (PMID 21208426, 2011). "Both PPARG and HNF1A are known susceptibility genes for type 2 diabetes." (PMID 22216000, 2011). "Thus, HNF1A G319S is associated with the future development of type 2 diabetes in this Aboriginal population, and this association is amplified in the presence of cigarette smoking." (PMID 21208426, 2011). "The HNF1A G319S variant is associated with incident type 2 diabetes in Aboriginal Canadians." (PMID 21208426, 2011). "HNF1A also has allelic associations with type 2 diabetes, CRP and coronary heart disease." (PMID 21943158, 2011). "Therefore, while HNF1A appears to influence CRP concentrations in the non-diabetic state, chronic elevation of CRP is unlikely mediating the association between the HNF1A polymorphism and the high prevalence of type 2 diabetes in this Aboriginal population." (PMID 20716378, 2010). "The aim of this study therefore was to determine whether CRP was mediating the association between HNF1A G319S and type 2 diabetes in an Aboriginal Canadian community known to have a high prevalence of type 2 diabetes." (PMID 20716378, 2010). "Moreover, linkageanalysis in combination with fine-mapping for susceptibility to multifactoriallate-onset type 2 diabetes has identified predisposing variants ofHNF4α and HNF1α in a growingnumber of studies." (PMID 19252740, 2009). "Variation in the P2 promoter of HNF4A, presumably leading to a decrease in HNF4A expression, has been associated with an increased risk of developing Type 2 diabetes, whilst bi-allelic inactivation of HNF1A and HNF1B has been shown to cause a number of types of cancer." (PMID 19787084, 2008). "The role of HNF1A variants in type 2 diabetes in the general population remains unclear." (PMID 36216889, 2023). "Our study highlights the importance of the location of functional variants in the HNF1A gene, the need for more and larger studies in populations of non-European ancestry, and the role of polygenic burden on the impact of rare HNF1A variants on type 2 diabetes risk and age of diagnosis." (PMID 36216889, 2023). "The templates for ROSA26 and HNF1a were designed to insert a novel 8-base-pair sequence containing a HindIII restriction endonuclease site, intended to replicate a premature termination codon as observed in common maturity onset diabetes of the young (MODY) alleles." (PMID 33584819, 2020). "Since HNF-1α protein plays a key role in β-cell function, the reduction in normal HNF-1α activity may compromise β-cell function and further explain the interaction between the HNF1A G319S polymorphism and fasting insulin on the outcome of incident type 2 diabetes observed in our study." (PMID 21208426, 2011). "However, it has not been investigated whether plasma CRP mediates the association between the HNF1A polymorphism and type 2 diabetes." (PMID 20716378, 2010). "In this study, we focussed on exons 8–10 of the HNF1A gene since rare, penetrant mutations in these exons (which are only transcribed in selected HNF1A isoforms) are associated with a later age of diagnosis of Maturity onset diabetes of the young (MODY) than mutations in exons 1–7." (PMID 19672314, 2009). "Pathogenic variants in these genes are associated with HNF1A-MODY and HNF4A-MODY, subtypes of maturity-onset diabetes of the young, as well as renal cysts and diabetes syndrome (RCAD), respectively." (PMID 39859454, 2025). "Of note, mutations in subtype-defining transcription factors, including HNF1A, TCF4, NEUROD1 and HNF4A, cause MODY, and their cis-regulatory sites map to type 2 diabetes risk loci." (PMID 40768044, 2025). "While FOXA2 has been shown to control mRNA levels of PDX1, HNF1A, and HNF4A, mutations in HNF1A, HNF1B, HNF4A, and PDX1 are known to cause maturity-onset diabetes of the young (MODY)." (PMID 39322760, 2024).
type 2 diabetes (continued). "A meta-analysis of 12 studies revealed a significant association between HNF1A GOF and a reduced likelihood of developing type 2 diabetes (odds ratio [OR] = 0.77, p = 0.007)." (PMID 39902162, 2024). "Rare variants in GCK, HNF1A and HNF4A are recognised as causes of maturity onset diabetes of the young." (PMID 39097650, 2024). "Crystal structure and transcriptional activation studies identify how HNF4A P2 promoter sequence variants bind HNF-1A and highlight disease mechanisms of P2-driven HNF1A-&ndash;maturity-onset diabetes of the young." (PMID 38855865, 2024). "We report the very first documented case of HNF1A maturity onset diabetes of the young in the sub-Saharan African region." (PMID 39420387, 2024). "Of note, heterozygous mutations in human HNF1A gene cause HNF1A-MODY (or MODY3), the most prevalent form of monogenic maturity onset diabetes." (PMID 38825059, 2024). "We calculated polygenic risk scores (PRSs) based on genome-wide association study summary statistics for type 2 diabetes, and examined the association of HNF1A variants and PRS with risk of type 2 diabetes and age of diagnosis." (PMID 36216889, 2023). "The difference in BMI in pediatric patients, expressed as a Z‐score, did not attain statistical significance for studies that compared GCK‐MODY and HNF1A‐MODY/type 2 diabetes, and this indicator was assessed only in proband studies." (PMID 37226652, 2023). "We used the ‘insulin secretion’ pPS of variants in eight genes associated with type 2 diabetes risk due to poor beta cell function: MTNR1B, HNF1A, GCK, TCF7L2, TMEM258, ADCY5, SLC3OA8 and ABO." (PMID 35247066, 2022). "Variants in the Hepatocyte Nuclear Factor 1 Alpha gene (HNF1A) are associated with lipoproteins levels and type 2 diabetes." (PMID 35109885, 2022). "Numerous large-scale genetic investigations have established those common variations of the HNF1A and HNF4A genes are also associated with type 2 diabetes, implying that they play a role in the etiology of both disorders." (PMID 36037214, 2022). "As far CRP is concerned, we co-authored a multicenter European study demonstrating that the CRP serum levels were significantly lower in HNF1A-MODY than in type 1 or type 2 diabetes." (PMID 36104811, 2022). "The assay has been optimized and its validity tested using 1000 clinical samples from a cohort of individuals with young-adult onset diabetes including cases with HNF1A-MODY." (PMID 34939081, 2022). "A randomized trial showed a fourfold decrease in blood glucose in HNF1A MODY patients compared to matched type 2 diabetes controls." (PMID 35445424, 2022). "Rare loss-of-function variants of HNF1A and HNF4A can cause the mendelian disorder mature-onset diabetes of the young." (PMID 35387486, 2022). "HNF1A-MODY (MODY3) is a type of maturity onset diabetes of the young (MODY) for which a glycan biomarker has been proposed for patient identification and stratification." (PMID 33765222, 2021). "Toaima D., Näke A., Wendenburg J., Praedicow K., Rohayem J., EngelK., Galler A., Gahr M., Lee-Kirsch M.A. Identification of novelGCK and HNF1A/TCF1 mutations and polymorphisms in Germanfamilies with maturity-onset diabetes of the young (MODY)." (PMID 33659812, 2020). "The regulation of lipid metabolism by HNF1α is a potential cause of its close association with the development of metabolic diseases such as NAFLD and type 2 diabetes." (PMID 31223625, 2019). "We examined 77 patients with HNF1A MODY, 88 with GCK MODY mutations, 99 with type 1 diabetes, and 92 with type 2 diabetes." (PMID 30778899, 2019). "We correctly classified 92.9% of patients with type 1 diabetes, 84.8% with type 2 diabetes, 64.9% HNF1A MODY, and 52.3% GCK MODY patients." (PMID 30778899, 2019). "Differences in glycaemic, insulin regulation indices, lipids and incretins in fasting and during post-prandial between HNF1α and controls or type 2 diabetes." (PMID 28493909, 2017).